SMPD1 (sphingomyelin phosphodiesterase 1)
Diseases named in the same sentence as SMPD1 in open-access papers (continued):
Sharing a sentence is not in itself a finding about the gene and the disease.
Niemann-Pick disease type A (52 papers, 2007 to 2025). Niemann-Pick disease type A is a very severe subtype of Niemann-Pick disease, an autosomal recessive lysosomal disease, and is characterized clinically by onset in infancy or early childhood with failure to thrive, hepatosplenomegaly, and rapidly progressive neurodegenerative disorders. "Acid sphingomyelinase deficiency (ASMD), also known as Niemann-Pick disease types A and B, is a rare autosomal recessive lysosomal storage disorder caused by SMPD1 mutations." (PMID 41208004, 2025). "Acid sphingomyelinase deficiency (ASMD), formerly known as Niemann–Pick disease types A and B, is an autosomal recessive disorder caused by pathogenic variants in the sphingomyelin phosphodiesterase 1 (SMPD1) gene." (PMID 39728399, 2024). "Acid sphingomyelinase deficiency (ASMD) or Niemann–Pick disease types A, A/B, and B is a progressive, life-limiting, autosomal recessive disorder caused by sphingomyelin phosphodiesterase 1 (SMPD1) gene mutations." (PMID 39103853, 2024). "Niemann-Pick Disease types A and B are allelic disorders caused by mutations in the sphingomyelin phosphodiesterase-1 (SMPD1) gene." (PMID 38291356, 2024). "Niemann–Pick disease types A and B result from mutations in the SMPD1 gene, leading to acid sphingomyelinase deficiency and consequent accumulation of sphingomyelin." (PMID 39456198, 2024). "SMPD1 - two heterozygous variants in exons 4 and 6 (c.1311G>A and c.1757G>C) causing Niemann-Pick disease type A, an autosomal recessive disorder with one variant classified as pathogenic and the other as uncertain significance." (PMID 37519562, 2023). "Acid Sphingomyelinase Deficiency (ASMD) is a rare autosomal recessive disorder caused by mutations in the SMPD1 gene." (PMID 37069638, 2023). "Nowadays, hundreds of mutations in the SMPD1 gene coding for ASM have been identified to cause SM accumulation with the onset of Niemann-Pick disease type A and B (NPA and NPB)." (PMID 35727525, 2022). "Mutations in the SMPD1 gene cause Niemann–Pick disease types A and B. They produce a deficiency in the lysosomal enzyme acid sphingomyelinase activity that breaks down the lipid sphingomyelin in ceramide and phosphorylcholine." (PMID 34445564, 2021). "Acid sphingomyelinase deficiency is a pan-ethic disease associated with more than 200 SMPD1 gene variants." (PMID 34884674, 2021). "Significant advances in delineating the relationship between mutations in the SMPD1 gene, which causes Niemann–Pick disease types A and B, and PD have been reported in the past few years, with SMPD1 repeatedly identified as a genetic risk factor for PD." (PMID 32674335, 2020). "Niemann-Pick disease type A (NPA) is a rare autosomal recessive lysosomal storage disease caused by mutations in the SMPD1 gene, which encodes for the protein acid sphingomyelinase." (PMID 31132580, 2019). "Mutations in SMPD1 lead to Niemann-Pick disease type A or B and accumulation of sphingomyelin, and are also associated with increased risk for PD." (PMID 31649605, 2019). "In human, loss of acid sphingomyelinase (ASM/SMPD1) causes Niemann–Pick disease, type A. ASM hydrolyzes sphingomyelins to produce ceramides but protein targets of ASM remain largely unclear." (PMID 31142470, 2019). "In one of the families, a homozygous variant (c.340G>A; p.Val114Met) was identified in SMPD1 (Niemann-Pick disease type A/B; reference sequence NM_000543.4)." (PMID 28255779, 2017). "Sphingomyelinase deficiency was detected in two patients who were subsequently diagnosed with Niemann-Pick disease type B based on SMPD1 gene mutation analysis." (PMID 28222799, 2017). "In humans, mutation of the SMPD1 gene results in deficiency of A-SMase activity leading to Niemann-Pick disease types A and B, a highly lethal illness." (PMID 21566746, 2008). "Niemann-Pick disease type A and B is caused by a deficiency of acid sphingomyelinase due to mutations in the sphingomyelin phosphodiesterase-1 (SMPD1) gene." (PMID 18088425, 2007).
Niemann-Pick disease type A (continued). "Rare mutations at the SMPD1 gene can cause Niemann-Pick disease type A or B, which can differ in degrees of neurological impairment." (PMID 18088425, 2007). "Niemann-Pick disease type A and B is caused by a deficiency of the enzyme acid sphingomyelinase coded by SMPD1 gene." (PMID 18088425, 2007). "Forty-five mutations in SMPD1 gene causing different forms of Niemann-Pick disease type A and B have been described." (PMID 18088425, 2007). "PSP may be linked with pathogenic sphingomyelin phosphodiesterase 1 (SMPD1) variants associated with Niemann–Pick disease types A and B as its recessive cause." (PMID 40362170, 2025). "Acid sphingomyelinase deficiency (ASMD), historically known as Niemann–Pick disease types A, A/B, and B, is a rare lysosomal storage disease resulting from the deficiency of lysosomal enzyme acid sphingomyelinase (ASM) due to pathogenic variants in the sphingomyelin phosphodiesterase 1 (SMPD1) gene." (PMID 38615062, 2024). "In humans, the complete loss of Asm activity in subjects exhibiting autosomally recessive SMPD1 mutations results in Niemann-Pick disease type-A, characterized by neurodegeneration of the cerebral and cerebellar cortex, basal ganglia, brain stem and spinal cord with ataxia, dysarthria and dysphagia." (PMID 33057972, 2020). "Three subtypes of the disease are described: Niemann-Pick disease type A and Niemann-Pick disease type B are allelic disorders caused by mutations in the sphingomyelin phosphodiesterase-1 (SMPD1) gene, characterized by a primary deficiency of acid sphingomyelinase activity." (PMID 30650529, 2019). "Acid sphingomyelinase deficiency (ASMD), also known as Niemann Pick disease type A and type B, is a rare lysosomal storage disorder resulting from deficiency of the lysosomal enzyme acid sphingomyelinase (ASM) due to bi-allelic mutations in the sphingomyelin phosphodiesterase 1 gene, SMPD1." (PMID 30514648, 2019). "In addition to GBA, other lysosomal proteins have been associated with PD, e.g., acid sphingomyelinase (SMPD1, deficient in Niemann-Pick disease types A and B) and LIMP-2, a GCase transporter." (PMID 28212433, 2017). "Our data suggest that while rare mutations at the SMPD1 locus can cause Niemann-Pick disease types A and B and the concomitant low HDL-cholesterol, the two common coding non-synonymous variants that we examined at this locus do not appear to influence HDL-cholesterol levels to any great extent." (PMID 18088425, 2007). "Acid Sphingomyelinase Deficiency (ASMD, OMIM 607616), also known as Niemann‐Pick disease types A and B, is a rare lysosomal storage disorder caused by two bi‐allelic mutations in the SMPD1 gene resulting in a deficiency of acid sphingomyelinase (EC 3.1.4.12)." (PMID 40717061, 2025). "Acid Sphingomyelinase Deficiency (ASMD; alternatively known as Niemann–Pick Disease Types A, B and A/B, OMID# 257,200 and 607,616) is an ultra-rare multisystem genetic disorder caused by pathogenic variants of the SMPD1 gene." (PMID 37069638, 2023). "These included recurrent disease-causing variants for glycogen storage disease IIIa/IIIb (AGL), progressive familial intrahepatic cholestasis type 1 (ATP8B1), and Niemann–Pick disease type A/B (SMPD1)." (PMID 33083013, 2020). "Niemann-Pick disease type A (NPA) is a rare autosomal recessive, neuropathic lysosomal storage disease that is caused by mutations in the SMPD1 gene, leading to a deficiency in acid sphingomyelinase (< 10% enzyme activity) in the cells." (PMID 31132580, 2019). "Loss-of-function mutations in the sphingomyelin phosphodiesterase 1 (SMPD1) gene are associated with decreased catalytic activity of acid sphingomyelinase (ASM) and are the cause of the autosomal recessive lysosomal storage disorder Niemann-Pick disease types A and B (NPD)." (PMID 26084044, 2015).
Niemann-Pick disease type A (continued). "Although rare mutations in the SMPD1 gene can impair the function of acid sphingomyelinase and result in Niemann-Pick disease type A or B, as well as in low HDL-cholesterol, it is not known whether common amino acid change variants in SMPD1 can modulate HDL-cholesterol levels within a population." (PMID 18088425, 2007).
lysosomal storage disorder (50 papers, 2008 to 2026). "Acid sphingomyelinase deficiency (ASMD) is a rare lysosomal storage disorder caused by SMPD1 mutations, resulting in sphingomyelin accumulation and diverse manifestations." (PMID 41029409, 2025). "Acid sphingomyelinase deficiency (ASMD) type A/B, a rare lysosomal storage disorder caused by biallelic mutations in the SMPD1 gene, presents with variable visceral and neurological manifestations." (PMID 40927581, 2025). "ASMD is a rare lysosomal storage disorder resulting from mutations in the SMPD1 gene, leading to deficient ASM activity and subsequent sphingomyelin accumulation in multiple tissues." (PMID 41208004, 2025). "Acid Sphingomyelinase Deficiency (ASMD) type B is a rare lysosomal disorder caused by SMPD1 mutations." (PMID 40420295, 2025). "Acid sphingomyelinase deficiency (ASMD, Niemann-Pick) is a rare autosomal recessive lysosomal storage disorder (LSD) caused by mutations in the SMPD1 gene, which codes for ASM." (PMID 38303068, 2024). "Acid sphingomyelinase deficiency (ASMD) is a lysosomal storage disorder caused by mutations in the SMPD1 gene encoding for the acid sphingomyelinase (ASM)." (PMID 37024473, 2023). "Acid sphingomyelinase deficiency (ASMD) is an autosomal recessive lysosomal storage disease resulting from biallelic pathogenic variants in the SMPD1 gene encoding the lysosomal enzyme acid sphingomyelinase (ASM)." (PMID 37098529, 2023). "The lysosomal storage disorder Niemann Pick (NP) disease type B results from mutations in the sphingomyelin phosphodiesterase 1 (SMPD1) gene, while NP disease types C1 and C2 result from mutations in the NPC1 and NPC2 genes, respectively." (PMID 31698146, 2020). "SMPD1 encodes for sphingomyelin phosphodiesterase 1 (acid sphingomyelinase), enzyme that has been implicated in the pathology of Niemann–Pick types A and B lysosomal storage disorders (MIM 257200 and 607616), inherited as autosomal recessive traits." (PMID 32661301, 2020). "Niemann-Pick disease type B (NPB) is a rare autosomal recessive lysosomal storage disease caused by mutations in the SMPD1 gene, which encodes for acid sphingomyelinase." (PMID 31009819, 2019). "Acid sphingomyelinase deficiency (ASMD), a rare lysosomal storage disease, is an autosomal recessive genetic disorder caused by different SMPD1 mutations." (PMID 28228103, 2017). "Niemann-Pick disease type B (NPD-B) is a rare lysosomal storage disorder caused by biallelic mutations in the SMPD1 gene, leading to deficient acid sphingomyelinase activity and lipid accumulation in various organs." (PMID 41211123, 2025). "Variants in the sphingomyelin phosphodiesterase 1 (SMPD1) gene lead to the type A and B forms of lysosomal storage disorder NPD." (PMID 36725747, 2023). "Pathogenic SMPD1 variants are mainly involved in NPD, a lysosomal storage disease characterized by a birth prevalence of about 0.5/100,000." (PMID 33925997, 2021). "Niemann-Pick disease type B (NPB) is a rare autosomal recessive, lysosomal storage disease that is caused by mutations in the SMPD1 gene, leading to a deficiency in acid sphingomyelinase in the lysosome of patient cells." (PMID 31009819, 2019). "Acid sphingomyelinase (ASM) deficiency (ASMD), a rare lysosomal storage disease, is an autosomal recessive genetic disorder caused by mutations in the SMPD1 gene." (PMID 28228103, 2017). "Acid Sphingomyelinase Deficiency (ASMD) type B is a non-neuronopathic lysosomal storage disorder caused by deficient acid sphingomyelinase activity due to biallelic pathogenic variants in the SMPD1 (Sphingomyelin Phosphodiesterase 1) gene." (PMID 40420295, 2025).
lysosomal storage disorder (continued). "Mutations in acid sphingomyelinase (aSMase), encoded by SMPD1, are causative of the NPD type A and B forms, whereas NPD type C, a lysosomal storage disease distinct from sphingolipidoses, is a cholesterol trafficking defect due to mutations in NPC1 or NPC2 genes." (PMID 36902174, 2023). "Note that NPD of types C and D are also lysosomal storage diseases but are not linked to SMPD1, and are thus not discussed in this paper." (PMID 33925997, 2021). "A recent study that assessed the association of specific founder mutations in each of the lysosomal storage disorder genes HEXA, SMPD1 and MCOLN1, in 938 Ashkenazi Jewish (AJ) PD patients and 282 matched AJ controls, reported SMPD1 L302P as a risk factor for PD in the AJ population." (PMID 25933391, 2015). "In the current study we performed a genetic analysis of four lysosomal storage disorder genes including GBA, HEXA, SMPD1, MCOLN1 in 231 brain autopsies from the New York Brain Bank at Columbia University." (PMID 25933391, 2015).
acid sphingomyelinase deficiency (32 papers, 2013 to 2026). "Acid sphingomyelinase deficiency (ASMD) is an autosomal recessive disease caused by biallelic pathogenic variants in the sphingomyelin phosphodiesterase-1 (SMPD1) gene." (PMID 37347058, 2023). "Acid sphingomyelinase deficiency (ASMD) is an autosomal recessive lysosomal storage disorder resulting from disease-causing variants in the SMPD1 gene (EC3.1.4.12) encoding ASM." (PMID 38042851, 2023). "NPD type A and B are also known as a SMPD1-associated disease which constitutes different clinical phenotypes of a primary sphingomyelin storage disorder resulting from acid sphingomyelinase deficiency due to SMPD1 gene mutations." (PMID 31037088, 2019). "Acid sphingomyelinase deficiency (ASMD) disorder, also known as Niemann–Pick disease (NPD) is a rare genetic disease caused by mutations in SMPD1 gene, which encodes sphingomyelin phosphodiesterase (ASM)." (PMID 36907956, 2023). "The chronic visceral subtype of acid sphingomyelinase deficiency, also called Niemann Pick disease type B (NPDB), is a rare autosomal recessive hereditary disease that is caused by mutations in the SMPD1 gene." (PMID 36114502, 2022). "The chronic visceral subtype of acid sphingomyelinase deficiency, commonly known as Niemann Pick disease type B (NPDB), is a relatively rare autosomal recessive genetic disorder that is caused by mutations in the SMPD1 gene." (PMID 36114502, 2022). "Acid sphingomyelinase deficiency (ASMD), a rare lysosomal storage disease, results from mutations in SMPD1, the gene encoding acid sphingomyelinase (ASM)." (PMID 30514648, 2019). "Acid sphingomyelinase deficiency (ASMD), an autosomal recessive lysosomal storage disorder, results from mutations in the SMPD1 gene encoding the lysosomal enzyme acid sphingomyelinase (ASM)." (PMID 29305734, 2018). "Acid sphingomyelinase deficiency (ASMD) is a rare lysosomal storage disorder that leads to the accumulation of sphingomyelin (and other lipids) in cells and tissues due to deficient acid sphingomyelinase activity (ASM, SMPD1; EC 3.1.4.12)." (PMID 33971920, 2021). "Acid sphingomyelinase deficiency (ASMD), due to mutations in the sphingomyelin phosphodiesterase 1 (SMPD1) gene, is divided into infantile neurovisceral ASMD (Niemann-Pick type A), chronic neurovisceral ASMD (intermediate form, Niemann-Pick type A/B) and chronic visceral ASMD (Niemann-Pick type B)." (PMID 30795770, 2019).
depression (28 papers, 2014 to 2025). "We would like to stress that SMPD1 is a promising drug target, as its dysregulation is related to a large number of yet other diseases that range from major depression to Alzheimer disease and from atherosclerosis to various cancers." (PMID 33925997, 2021). "Interestingly, growing support for a connection between SMPD1 and a wide series of aging and age-related neurodegenerative diseases is found in the literature; these include Parkinson disease, Alzheimer disease and major depression." (PMID 33925997, 2021). "The post hoc analysis revealed a trend towards increased SMPD1 mRNA expression in severely depressed patients as compared with individuals without clinical depression (p = 0.09)." (PMID 34071826, 2021). "Moreover, SMPD1 splicing has been reported to influence ASM activity and be altered in major depression." (PMID 30551571, 2018).
COVID-19 (21 papers, 2021 to 2025). A disease caused by infection with severe acute respiratory syndrome coronavirus 2. "Upregulation of SMPD1 activity and ceramide have been noted in COVID-19 patients requiring intensive care." (PMID 36143338, 2022).
melanoma (21 papers, 2013 to 2025). A malignant, usually aggressive tumor composed of atypical, neoplastic melanocytes. "To analyze the impact of Asm activity on T cell function during tumorigenesis, we transplanted B16-F1 melanoma cells into Smpd1-deficient mice (Asm-KO) or control (Asm-WT) littermates." (PMID 36426850, 2022). "(A) B16-F1 melanoma cells were transplanted into Smpd1-deficient mice (Asm-KO) mice and control littermates (Asm-WT)." (PMID 36426850, 2022). "Downregulation of SMPD1 has been associated with reduced tumor growth, impaired metastasis, and altered Met receptor trafficking, suggesting that miR-16 may suppress melanoma progression by disrupting these pathways." (PMID 40647495, 2025). "Transplanting wild-type platelets and melanoma cells into Smpd1 knockout mice reinvigorated melanoma metastasis." (PMID 34281263, 2021). "Transplantation of melanoma cells into wild-type mice showed multiple lung metastases, while Smpd1 knockout mice were protected under the same conditions." (PMID 34281263, 2021). "In marked contrast, tumor metastasis was almost completely absent after B16F10 melanoma cells were injected into syngeneic Asm-deficient mice (Smpd1−/− mice) (Fig1A and B)." (PMID 25851537, 2015). "Transient overexpression of miR-16 resulted in a significant reduction in SMPD1 and VTI1B levels in melanoma cell lines." (PMID 40647495, 2025). "Last, we analyzed the protein level of SMPD1 (ASM) and VTI1B in two melanoma cell lines overexpressing miR-16, using Western blot analysis." (PMID 40647495, 2025).